RPUSD1 (RNA pseudouridine synthase domain containing 1)
Description:
Pseudouridylate synthase that catalyzes the conversion of uridine to pseudouridine in cytoplasmic tRNAs. Catalyzes pseudouridylation of pseudouridine-30 and pseudouridine-72 from uracil-30 and uracil-72 within the anticodon stem of cytoplasmic tRNAs.
Synonyms: C16orf40; RLUCL; MGC19600
Tractability: PROTAC: ubiquitination databases record sites on it.
Gene: Protein-coding gene on chromosome 16 (784,974 to 788,406, reverse strand). Ensembl gene ENSG00000007376.
Subcellular location (Human Protein Atlas): Golgi apparatus; Cell Junctions; Cytosol; Nucleoplasm
Gene Ontology:
Molecular function: protein binding; tRNA pseudouridine synthase activity; pseudouridine synthase activity; RNA binding
Biological process: tRNA pseudouridine synthesis; enzyme-directed rRNA pseudouridine synthesis; pseudouridine synthesis; RNA modification
Genetic constraint (gnomAD): Loss-of-function variants: 28 observed, 19.76 expected, observed/expected ratio (o/e) 1.42, 90% interval 1.04 to 1.86. The synonymous counts are far from expectation, so gnomAD's model fits this gene poorly and the ratio says little. Missense variants: 596 observed, 423.78 expected, observed/expected ratio (o/e) 1.41, 90% interval 1.31 to 1.5. Synonymous variants: 298 observed, 189.93 expected, observed/expected ratio (o/e) 1.57, 90% interval 1.43 to 1.73.
Homologues: Orthologues: chimpanzee RPUSD1 (99% identical), macaque RPUSD1 (97% identical), pig RPUSD1 (86% identical), rat Rpusd1 (83% identical), mouse Rpusd1 (82% identical), guinea pig RPUSD1 (82% identical), dog RPUSD1 (81% identical), tropical clawed frog rpusd1 (59% identical), zebrafish rpusd1 (57% identical). Paralogues in human: RPUSD2 (22% identical), RPUSD4 (21% identical), RPUSD3 (20% identical).
Diseases named in the same sentence as RPUSD1 in open-access papers:
RPUSD1 is named in the same sentence as 7 diseases in open-access papers, as found by Europe PMC text mining. Sharing a sentence is not in itself a finding about the gene and the disease. The quoted sentences say what the papers report.
glioma (1 paper, 2021). A benign or malignant brain and spinal cord tumor that arises from glial cells (astrocytes, oligodendrocytes, ependymal cells). "Six Ψ synthase genes were associated with the prognosis, of which the expression of PUS1, PUS7, RPUSD1 and RPUSD3 was positively associated with the malignancy of glioma (HR > 1), and TRUB1 was negatively associated with the malignant grade (HR < 1)." (PMID 35118063, 2021). "The expression levels of RPUSD1 and DKC1 in high-grade gliomas were higher than that in low-grade gliomas." (PMID 35118063, 2021).
pancreatic cancer (1 paper, 2022). "Six genes, EARS2, ARL6IP1, DNAJA3, KNOP1, RPUSD1, and TMEM186, significantly coexpressed with PALB2 in both breast and pancreatic cancer." (PMID 35779338, 2022).
renal carcinoma (1 paper, 2023). A carcinoma arising from the epithelium of the renal parenchyma or the renal pelvis. "According to our findings, the expression of PUS1, PUS7, DKC1 and RPUSD1 is highly expressed in most cancer types, and among those genes, the expression of PUS1, PUS7 and RPUSD1 is markedly upregulated in renal cancers, including KICH, KIRC and KIRP." (PMID 37315299, 2023).
tumor (4 papers, 2021 to 2026). "Strikingly, patients exhibiting elevated levels of PUS1, PUS3, PUSL1, RPUSD1-4, and TRUB2 demonstrated a significantly shorter disease-free survival, as evidenced by combined analysis with tumor disease-free survival data." (PMID 39247811, 2024). "The results suggest that PUS family members, including PUS1, RPUSD1, RPUSD3, and PUS7, may contribute to both enhanced tumour stemness and the establishment of an immunosuppressive microenvironment in PAAD." (PMID 41496500, 2026). "In the GSE59612 dataset, the expression of PUS1, PUS7, RPUSD1 and DKC1 were significantly increased in the tumor core tissues relative to tumor marginal tissues and paracancerous tissues; and the expression of TRUB1 was decreased from paracancerous tissue to tumor core tissue." (PMID 35118063, 2021).
cancer (2 papers, 2023 to 2026). A tumor composed of atypical neoplastic, often pleomorphic cells that invade other tissues. "RPUSD1 exhibited markedly elevated expression across pan‐cancer tissues, followed by TRUB2, TRUB1, and PUS3." (PMID 41496500, 2026).
RPUSD1 also shares sentences with these, for which no sentence is quoted: prostate adenocarcinoma (1 paper); prostate carcinoma (1).